FAM240B (family with sequence similarity 240 member B)
Gene: Protein-coding gene on chromosome 9 (38,694,266 to 38,720,133, reverse strand). Ensembl gene ENSG00000283329.
Homologues: Orthologues: chimpanzee FAM240B (100% identical), macaque FAM240B (95% identical), dog FAM240B (81% identical), rabbit FAM240B (81% identical), guinea pig FAM240B (79% identical), pig FAM240B (79% identical), mouse Fam240b (77% identical), rat Fam240b (77% identical). Paralogues in human: FAM240A (64% identical).